GATA4 (GATA binding protein 4)
Diseases named in the same sentence as GATA4 in open-access papers (continued):
Sharing a sentence is not in itself a finding about the gene and the disease.
cardiac hypertrophy (continued). "In the current investigation, we decided to determine whether gentisic acid from this extract affects the Sp1/GATA4 pathway in pressure overload‐induced cardiac hypertrophy." (PMID 30256522, 2018). "Furthermore, Zbtb16 is known to regulate GATA4 transcription and has a proposed role in cardiac hypertrophy." (PMID 30410445, 2018). "The results confirm that ISO induced cardiac-hypertrophy by elevating the levels of hypertrophy associated proteins, ANP and BNP and further by upregulating p-CaMKII, calcineurin, p-GATA4 and NFATc3 which was correlated with a significant enlargement of the H9c2 cardiomyoblast." (PMID 28863192, 2017). "Atropine abolished the effect of pyridostigmine on CaN/NFAT3/GATA4 in cardiac hypertrophy." (PMID 28296184, 2017). "Western blot analysis was performed to assess the role of CaN/NFAT3/GATA4 in cardiac hypertrophy." (PMID 28296184, 2017). "The effect of pyridostigmine on the sympathetic nerve may lead to CaN/NFAT3/GATA4 signalling cascade inhibition and subsequent amelioration of cardiac hypertrophy." (PMID 28296184, 2017). "In the present study, pyridostigmine may have suppressed the formation of Orai1/STIM1 complex, resulting in inhibition of the activation of the CaN/NFAT3/GATA4 signalling pathway and attenuation of cardiac hypertrophy." (PMID 28296184, 2017). "Consequently, the transcription of downstream targets such as NPPA and GATA4 is initiated and pathological cardiac hypertrophy is established." (PMID 26582913, 2016). "For instance, GATA4 regulates cardiac fetal genes and stress-induced cardiac hypertrophy in vivo." (PMID 26582913, 2016). "Prophylactic resistance training attenuated most of these changes, except angiotensin II, fibrosis, heart rate and concentric remodeling of left ventricle, confirmed by the increased of NFATc3 and GATA-4, proteins involved in the pathologic cardiac hypertrophy pathway." (PMID 27880816, 2016). "GATA4 is an important transcription factor mediating cardiac hypertrophy." (PMID 25830299, 2015). "The transcription factor GATA4 is an important regulator of stimuli induced cardiac hypertrophy." (PMID 26257652, 2015). "Stress overload of TAC could activate the phosphorylation of the protein kinases of ERK1/2 and AKT, enhance the expression of GATA4, promote the transcription of hypertrophic gene, and result in cardiac hypertrophy and fibrosis." (PMID 25093027, 2014). "AT could inhibit the phosphorylation of ERK1/2 and AKT, reduce GATA4, and inhibit pathological development of cardiac hypertrophy." (PMID 25093027, 2014). "In this line of evidence, our report clearly shows that sorafenib suppressed expression of both the pro-hypertrophic effector ANP and its transcription factor GATA4, and that sorafenib may therefore be an interesting treatment strategy for cardiac hypertrophy." (PMID 24885948, 2014). "GATA-4 binding sites are thought to be required for activation of β-MHC and angiotensin II type a receptor expression - both of which have been implicated in pathological ventricular hypertrophy and the over expression of GATA-4 generated cardiac hypertrophy in cultured cardiomyocytes and in mice." (PMID 22792196, 2012). "GATA-4 is one of first transcription factors expressed in cardiac cells and plays an important role in transcriptional regulation during cardiac development and growth as well as in cardiac hypertrophy and heart failure." (PMID 22758628, 2011). "GATA-4 induces several promoters that are activated during cardiac hypertrophy." (PMID 22758628, 2011). "However, overexpression of GATA4 expression significantly reversed the lactylation inhibition attenuated cardiac hypertrophy in TAC mice, as evidenced by decreased cardiac function, increased HW/BW and LV/TL ratios, and normalized cardiomyocyte sizes by H&E and WGA staining of heart sections." (PMID 41143277, 2025).
cardiac hypertrophy (continued). "Given the multifunctional nature of GATA4 as a transcription factor and the role of H3K18la in gene expression regulation, this study aims to elucidate the intricate interplay between H3K18la lactylation and GATA4 signaling pathways in the context of cardiac hypertrophy." (PMID 41143277, 2025). "However, genes associated with cardiac hypertrophy, including GATA4, MYH7, and NPPA, were not differentially expressed in the LV." (PMID 36924351, 2025). "Considering that GATA4 regulates the expression of genes involved in myocardial contraction and promotes cardiac hypertrophy in response to hemodynamic stress, this could be interpreted as a sign of myocardial maintenance or the readiness to adapt to changing hemodynamics." (PMID 40650272, 2025). "Furthermore, the co-occurrence of GATA4 and H3K27ac at the chromatin has been investigated in the context of cardiac hypertrophy, illustrating GATA4’s role in regulating H3K27ac deposition by recruiting p300/CBP to active regulatory regions, particularly enhancers." (PMID 39456519, 2024). "GATA4 regulates neonatal heart regeneration through regulating expression of FGF16, and overexpression of FGF16 via adeno-associated virus in Gata4-ablated mice heart could partially rescue cardiac hypertrophy and improve cardiac function after injury." (PMID 39544432, 2024). "GATA4 is a transcription factor that regulates signal response processes in many organs, such as cardiac precursor cell differentiation, cardiac development, cardiac hypertrophy, and resistance to apoptosis, as well as mediating the effects of genetic mutations caused by congenital heart disease." (PMID 36177479, 2022). "Overexpression of either GATA4 or GATA6 could induce cardiac hypertrophy both in vitro and in vivo." (PMID 34054926, 2021). "Therefore, pyridostigmine may inhibit the CaN/NFAT3/GATA4 signalling pathway by suppressing the activation of the renin angiotensin system, resulting in amelioration of cardiac hypertrophy." (PMID 28296184, 2017). "Ppp3ca has been shown to be a key regulator of cardiac hypertrophy through activation of the transcription factor NFAT (nuclear factor of activated T-cells) which promotes the expression of pro-hypertrophic genes in concert with other transcription factors such as GATA4 and MEF2." (PMID 20937113, 2010). "Prior research indicates that GATA4, a nuclear transcription factor, facilitates the expression of hypertrophic genes such as MYH7 and BNP, which ultimately contribute to myocardial hypertrophy." (PMID 40753540, 2025). "The intersection of these databases yielded genes known to be involved in cardiac hypertrophy, including EZH2, NFATc4, GATA4, and JARID2." (PMID 38810124, 2024). "MiR-26b modulates GATA Binding Protein 4 (GATA4) expression through a post-transcriptional mechanism, which is essential for the growth and survival of myocytes during cardiac hypertrophy." (PMID 38672166, 2024). "Pathological cardiac hypertrophy and heart failure are characterized by calcineurin overexpression in the heart and activation of the calcineurin/NFAT and GATA4 pathway." (PMID 39408900, 2024). "This study demonstrates that TGW mitigates cardiac hypertrophy by influencing key hypertrophy markers and regulating critical signaling pathways, including calcineurin/NFAT and GATA-4." (PMID 39408900, 2024). "This resulted in the identification of KLF-4 interactions with genes like GATA4, MEF2C, TBX5, NKX2.5, and SRF, all of which are known regulators of cardiac hypertrophy and pro-hypertrophic pathways." (PMID 38672763, 2024). "We examined cardiac hypertrophy-related genes and found that the mRNA levels of BNP (Natriuretic Peptide B), Myh7 (Myosin Heavy Chain 7), and Gata4 (GATA Binding Protein 4) were significantly up-regulated in maternal DHT-treated group." (PMID 37642904, 2024).
cardiac hypertrophy (continued). "Upon stimulation of the hypertrophic response, calcineurin dephosphorylates NFAT transcription factor, which then translocates into the nucleus to form a complex with GATA-binding protein 4 (GATA4), a key molecule modulating cardiac hypertrophy-related genes." (PMID 36675993, 2022). "The HAT complex on one hand cooperates with transcription factors such as MEF2C, GATA4, and HIF1, and binds to transcriptional regulation elements such as promoters or enhancers to participate in cardiac hypertrophy." (PMID 35958418, 2022). "The p-GATA4 can initiate the expression of hypertrophy response genes such as ANP and β-MHC, which participate in the development of myocardial hypertrophy." (PMID 34690749, 2021). "Here, we show that fibroblast GATA-4 and GATA-6 promote adaptive remodeling in pressure overload induced cardiac hypertrophy." (PMID 33876316, 2021). "Others have shown that the SIRT3-dependent activation of anti-oxidative Foxo3a targets Ras activation and represses the activity of transcription factors such as GATA4 and NFAT involved in the development of cardiac hypertrophy." (PMID 32429302, 2020). "The results of recent study indicated that DOX deplete the transcription factor GATA4 in cardiomyocytes, and restoration of GATA-4 levels prevents DOX-induced myocardial hypertrophy and cell death." (PMID 33374365, 2020). "GA significantly ameliorated cardiac function and inhibited cardiac hypertrophy and fibrosis by disruption of PI3K–Akt–GSK3β and MEK1/2–ERK1/2– GATA4 signaling and via Ang II stimulation." (PMID 33328989, 2020). "Conversely, these latter genes together with GATA4 and HAND2 resulted upregulated in V samples, belonging to functional categories of heart development and cardiac hypertrophy." (PMID 31975556, 2020). "GATA4 acetylation by p300/CBP stimulates GATA4 transcriptional activation and promotes pathological cardiac gene expression leading to cardiac hypertrophy." (PMID 30126190, 2018). "Gene reporter studies show that KLF15 inhibits MEF2 and GATA4 DNA-binding transcriptional activation and that KLF15 negatively regulates cardiac hypertrophy by preventing DNA-binding of MEF2 and GATA4 to their transcriptional targets." (PMID 29702551, 2018). "In our study, pyridostigmine inhibited the expression of CaN, NFAT3, p‐GATA4 and STIM1, prevented Orai1/STIM1 complex formation and attenuated cardiac hypertrophy." (PMID 28296184, 2017). "Recent studies highlight that ERK phosphorylates GATA4 at S105, leading to enhanced GATA4-DNA binding and activation of ERK1/2-induced cardiac hypertrophy." (PMID 26973524, 2016). "ERK directly phosphorylates Ser-105 in GATA-4 and dominant negative GATA-4 attenuated activated MEK1-induced myocyte growth, suggesting an important role of ERK in cardiac hypertrophy through GATA-4." (PMID 27195769, 2016). "Some studies have shown that gastrodin inhibited cardiac hypertrophy and fibrosis through inhibiting ERK1/2 signaling pathway and activation of GATA-4." (PMID 26587048, 2015). "For example, GATA-4 has been shown to modulate the transcriptional activation of angiotensin II type1A receptor and β-MHC in pressure overload-induced cardiac hypertrophy." (PMID 26557089, 2015). "GATA-4 also interacts with NFAT3, another transcription factor that is involved in promoting cardiac hypertrophy." (PMID 26557089, 2015). "Taken together the Ang II-AT2 exerted multiple convergent effects directed to cardiac hypertrophy through activation of p85α PI3K and p70S6k, inhibition of GSK3ß to facilitate nuclear localization of GATA4 and stimulation of GATA4 transcription." (PMID 22558183, 2012). "However, the role of GATA-4 in hyperglycemia-induced cardiac hypertrophy is still unknown." (PMID 21702924, 2011). "An inducible CM-specific Gata4 transgene overexpression (4.6-fold increase) showed mild cardiac hypertrophy, no fibrosis, unaltered FS, and increased angiogenesis." (PMID 40463063, 2025).
cardiac hypertrophy (continued). "Our investigation reveals that mice with Gata4 uORF inactivation manifest spontaneous cardiac hypertrophy without apparent fibrosis as they age." (PMID 40463063, 2025). "Additionally, quercetin lowered key cardiac hypertrophy mediators, including B-type natriuretic peptide (BNP), GATA-binding protein 4 (GATA4), and serum response factor." (PMID 39795285, 2024). "GATA-4 is a cardiac-restricted zinc finger protein that participates in cardiac development and related gene expression, and overexpression of GATA-4 is known to result in myocardial hypertrophy in vivo." (PMID 39408900, 2024). "Furthermore, a GATA4 uORF-targeting ASO upregulates cardiac GATA4 expression, which protects against cardiac hypertrophy." (PMID 39525088, 2024). "Interestingly, GATA4 and GATA6 have been reported to contribute to cardiac hypertrophy when overexpressed in cardiomyocytes, interacting with numerous cofactors under complex mechanisms." (PMID 37293953, 2023). "Therefore, this study has demonstrated for the first time that SJT blocks the cardiac hypertrophy induced by DOX, through the inhibition of the Calcineurin/NFAT/GATA4 pathway." (PMID 38137908, 2023). "The transcription factors GATA4, GATA6 and SP1 are reported to induce cardiac hypertrophy." (PMID 35719043, 2022). "Unlike BMP4, GATA4, another transcription factor related to cardiac hypertrophy, was downregulated in both groups fed an HCD." (PMID 35347086, 2022). "Some studies have that there are MAPK-targeted phosphorylation sites in the N-terminal transactivation domain of GATA4, which may be involved in the signal transduction process of MAPK during myocardial hypertrophy." (PMID 36177479, 2022). "The precise role of GATA4 has not yet been investigated in hyperglycemic-induced cardiac hypertrophy, although it has been identified as the main regulator of calcium signaling." (PMID 34885867, 2021). "As the contribution of fibroblasts and vessels is increasingly acknowledged in cardiac hypertrophy, the role of distinct cardiac transcription factors, such as GATA4 or GATA6, needs to be considered also in non-cardiomyocytes." (PMID 34089101, 2021). "Along with GATA4, MEF2, which comprises four members (MEF2a, -2b, -2c, and -2d) generated by alternative splicing, is considered as a core cardiogenic TF and master regulator of cardiac hypertrophy." (PMID 34208388, 2021). "GATA4 is a member of the GATA family of zinc finger transcription factor, which was originally discovered as a regulator of cardiac development and subsequently identified as a major regulator of cardiac hypertrophy and cell survival." (PMID 32185414, 2020). "It is reported that quercetin prevented cardiac hypertrophy by proteasome inhibition and activation of GSK-3α/β, which is related to upstream (AKT, LKB1/AMPKα) and downstream hypertrophic factors, such as ERK, histone H3, β-catenin, and GATA4." (PMID 31949472, 2019). "Also, a study reported that crocetin inhibited inflammation by blocking NF-κB signaling and diminished cardiac hypertrophy by blocking the reactive oxygen species (ROS)-dependent MAPK/ MEK/ERK1/2 pathway and GATA binding protein-4 (GATA-4) activation." (PMID 31223464, 2019). "Since GATA-4 is well known to promote cardiac hypertrophy, it is interesting to study whether leptin-induced vascular remodeling could be mediated by GATA-4, thus discovering a new role for GATA-4 in the vascular system." (PMID 26557089, 2015). "Acetylation of H3K9 and H3K27 has also been suggested to be involved in the expression of GATA4, as GATA4 is involved in the development of HF and the fetal gene is reactivated during HF, suggesting that the acetylation of H3K4 may be involved in cardiac hypertrophy and HF." (PMID 37008337, 2023).
cardiac hypertrophy (continued). "Nevertheless, the cardiomyocyte cross-sectional area similarly increased in Gata4/6fl-Per-Cre and control mice, indicating that the cellular mechanisms enabling compensatory cardiac hypertrophy do not depend on the expression levels of Gata4 and Gata6 in cardiac fibroblasts." (PMID 33876316, 2021). "Pyridostigmine attenuated cardiac hypertrophy and improved cardiac function, which was related to improved cholinergic transmission efficiency (decreased acetylcholinesterase and increased acetylcholine), inhibition of the CaN/NFAT3/GATA4 pathway and suppression of the interaction of Orai1/STIM1." (PMID 28296184, 2017). "Therefore, this study examined changes in vagal discharge and investigated whether pyridostigmine can inhibit CaN/NFAT3/GATA4 and suppress Orai1/STIM1 complex formation as well as improve cardiac function in pressure overload‐induced cardiac hypertrophy." (PMID 28296184, 2017). "In contrast, cardiac hypertrophy, pulmonary congestion, the abundance of macrophages, and α‐smooth‐muscle actin (αSMA)‐positive small conductance vessels were not significantly changed by Ad.GATA4 treatment (Fig EV4A–F)." (PMID 28053183, 2017). "Thus, in the adult heart GATA-4 and GATA-6 are each induced in a similar manner during stress-induced hypertrophy, but they do not appear to function together in a synergistic manner in driving cardiac hypertrophy more than either individual transgene." (PMID 24391969, 2013). "Finally, this phenomenon repressed the activity of both transcription factors, specifically GATA4 and NFAT, and translation factors, namely eukaryotic initiation factor 4E (elf4E) and ribosomal protein S6 kinase (PS6K), which are involved in the development of cardiac hypertrophy." (PMID 37558995, 2023). "Knock-in mice in which Serine 105 was replaced with alanine in GATA4 failed to develop cardiac hypertrophy in response to pressure overload or adrenergic stimulation with phenylephrine, suggesting that phosphorylation of GATA4 in this position is crucial for GATA4 function." (PMID 26257652, 2015). "Hybridized mice with knockout of GATA4 or GATA6 and overexpression of the other protein displayed partially reversed cardiac hypertrophy without full heart function recovery." (PMID 35185581, 2022).